CLPB (ClpB family mitochondrial disaggregase)
Description:
Functions as a regulatory ATPase and participates in secretion/protein trafficking process. Has ATP-dependent protein disaggregase activity and is required to maintain the solubility of key mitochondrial proteins. Involved in mitochondrial-mediated antiviral innate immunity, activates RIG-I-mediated signal transduction and production of IFNB1 and pro-inflammatory cytokine IL6. Plays a role in granulocyte differentiation.
Synonyms: SKD3; FLJ13152; ANKCLP; ANKCLB; HSP78; MEGCANN; MGCA7; MGCA7A; SCN9
Tractability: Small molecule: a structure with a bound ligand is known. PROTAC: ubiquitination databases record sites on it; its protein half-life has been measured.
Gene: Protein-coding gene on chromosome 11 (72,285,495 to 72,434,680, reverse strand). Ensembl gene ENSG00000162129.
Subcellular location: Mitochondrion intermembrane space
Gene Ontology:
Molecular function: ATP hydrolysis activity; ATP-dependent protein disaggregase activity; protein binding; ATP binding
Biological process: antiviral innate immune response; cellular response to heat; granulocyte differentiation; RIG-I signaling pathway
Cellular component: mitochondrial intermembrane space; mitochondrion
Genetic constraint (gnomAD): Loss-of-function variants: 36 observed, 73.97 expected, observed/expected ratio (o/e) 0.49, 90% interval 0.37 to 0.64. The upper end of that interval is the gene's LOEUF score, 0.64, which puts it in group 2 of 6, group 1 being the genes least tolerant of losing a copy. Missense variants: 773 observed, 908.64 expected, observed/expected ratio (o/e) 0.85, 90% interval 0.8 to 0.9. Synonymous variants: 331 observed, 363.06 expected, observed/expected ratio (o/e) 0.91, 90% interval 0.83 to 1.
Gene-disease validity (ClinGen):
ClinGen rates the evidence that CLPB causes each of these diseases.
Leigh syndrome (autosomal recessive): Limited. A progressive neurological disease defined by specific neuropathological features associating brainstem and basal ganglia lesions.
Homologues: Orthologues: macaque CLPB (97% identical), dog CLPB (93% identical), rabbit CLPB (91% identical), pig CLPB (90% identical), guinea pig CLPB (89% identical), rat Clpb (89% identical), mouse Clpb (88% identical), chimpanzee CLPB (82% identical), tropical clawed frog clpb (67% identical), zebrafish CLPB (36% identical).
Diseases named in the same sentence as CLPB in open-access papers:
CLPB is named in the same sentence as 62 diseases in open-access papers, as found by Europe PMC text mining. Sharing a sentence is not in itself a finding about the gene and the disease. The quoted sentences say what the papers report.
Obesity (12 papers, 2019 to 2026). Accumulation of substantial excess body fat. "The involvement of enterobacterial ClpB in the putative anti-obesity effects was studied using ClpB-deficient E.coli." (PMID 31911661, 2020). "The relative abundance (RA) of several phyla and families directly associated with ClpB was decreased in subjects with obesity." (PMID 32354351, 2020). "Such an α-MSH-like selectivity of the ClpB structure may underlie the link between a low abundance of Enterobacteriaceae in gut microbiota and obesity in humans." (PMID 31878078, 2019). "ClpB circulates in the blood and activates specific neurons expressing melanocortin receptor 4 to suppress appetite and obesity." (PMID 38933499, 2024). "Adding to this, because subjects with obesity exhibit lower ClpB levels, contributing to obesity-related metabolic dysfunction, it is important to assess Hafnia alvei HA4597TM supplementation in ClpB production on this target group." (PMID 37248499, 2023). "Summary of changes in autoantibodies against appetite-regulating hormones, the ClpB-mimetic protein, and neurotransmitters in AN, BN, depression, in healthy subjects, in obesity, and diabetes." (PMID 33953692, 2021). "Our data suggest that improved formulations of the CLPB protein and/or its fragments should be further evaluated for their potential utility in the therapeutic strategy against overweight and obesity." (PMID 34209507, 2021). "ClpB chaperone protein caseinolytic protease B (ClpB), which is found in Rikenellaceae and Clostridiaceae and are negatively related to obesity." (PMID 34346283, 2021). "Another bacterium from the Enterobacteriales family, Hafnia alvei (H. alvei), also produces the CLPB protein and exerts anorexigenic effects in preclinical models of obesity." (PMID 34209507, 2021). "In contrast to obesity, bacterial ClpB production was increased in mice with the activity-based anorexia and in food-restricted rats." (PMID 34205871, 2021). "The relevance of the enterobacterial ClpB gene to human obesity was studied by in silico analysis of fecal metagenomes of 569 healthy individuals from the “MetaHIT” database." (PMID 31911661, 2020). "Another anti-obesity effects of ClpB can be mediated via its systemic and central actions, including direct activation of the anorexigenic proopiomelanocortin (POMC) neurons of the hypothalamic arcuate nucleus." (PMID 31878078, 2019). "We have recently shown that ClpB was necessary for anorexigenic and anti-obesity effects of E.coli K12 in ob/ob mice fed a standard diet." (PMID 31878078, 2019). "Interestingly, gut microbiota of individuals with obesity have low abundance of enterobacterial ClpB, which can contribute to appetite dysregulation." (PMID 37248499, 2023). "In our study, metagenomic analysis of fecal microbiota revealed that the RA of Rikenellaceae, Clostridiaceae and not assigned Firmicutes were positively associated with ClpB gene function and were detected in lower relative abundance in subjects with obesity." (PMID 32354351, 2020). "In addition, to test the relevance of ClpB to the anti-obesity effects, in a separate experiment, ClpB-expressing and ClpB-deficient bacteria were supplied to ob/ob mice." (PMID 31911661, 2020). "Hafnia alvei HA4597TM could be a potential strain to be used as a probiotic after bariatric surgery based on its anti-obesity, satiety-inducing, and lowering glucose and cholesterol effects, which have been pointed out as consequences of increased levels of ClpB production." (PMID 37248499, 2023). "ClpB produced by intestinal microbes of obese patients is an α-MSH analog that inhibits appetite and obesity via its action in the CNS." (PMID 38933499, 2024). "Moreover, recent studies have reported that the probiotic strain Hafnia alvei HA4597® (HA), which produces the satietogenic peptide ClpB mimicking the effect of alpha-MSH, reduced weight gain and adiposity in rodent models of obesity." (PMID 34205871, 2021).
neutropenia (11 papers, 2017 to 2026). A decrease in the number of neutrophils found in the blood. "Loss-of-function CLPB mutations are associated with a few human diseases with neutropenia and neurological disorders." (PMID 36745679, 2023). "These two clinical signs are also present in subjects with MEGCANN (3-methylglutaconic aciduria with cataracts, neurologic involvement and neutropenia), which is caused by mutations in CLPB, an ATP-dependent refoldase (dissagregase) of the mitochondrial intermembrane space." (PMID 35096826, 2021). "Defects in CLPB could cause neurological involvement and neutropenia." (PMID 40909968, 2025). "Notably, biallelic autosomal recessive mutations in CLPB have been linked to 3-methylglutaconic aciduria, a severe mitochondrial disorder associated with increased levels of 3-methylglutaconic acid, neurological impairment, and occasionally neutropenia." (PMID 35499078, 2022). "All patients with heterozygous CLPB changes had neutropenia in childhood, but ANC ​​normalized with age." (PMID 41383606, 2025). "CLPB-related neutropenia also accounted for 10% of cases, followed by defects in the TCIRG1 (eight cases), CXCR4 (seven cases), and SRP72 genes (seven cases)." (PMID 41383606, 2025). "CLPB deficiency (CLPB, SKD3, biallelic variants, 3-methylglutaconic aciduria, type VIIA, autosomal dominant, 3-methylglutaconic aciduria, type VIIB, autosomal-recessive, neutropenia, severe congenital, 9, autosomal dominant, MIM #616254)." (PMID 40141413, 2025). "Dysfunction of the three AAA+ unfoldases CLPX, CLPB, and LONP1 causes distinctive features in peripheral tissues such as deficient heme biosynthesis, neutropenia, and collagen networks, respectively." (PMID 35954215, 2022). "Specifically, 2 severe-neutropenia-causing mutants in HAX1 and CLPB, L130 and Y272, respectively, emerge as key regulatory interaction sites enabling protein-protein formation." (PMID 35499078, 2022). "Defined variants clustered in the ANK domain of CLPB have previously been linked to the rare autosomal recessive mitochondrial disorder 3-methylglutaconic aciduria, type VII (MGCA7), associating neurological impairment and neutropenia." (PMID 35499078, 2022). "With the identification of L130 in HAX1 we thus verify 2 severe-neutropenia-causing mutants in HAX1 and CLPB, L130 and Y272, respectively, as essential residues for complex formation/stability and provide mechanistic evidence explaining a genotype-phenotype correlation." (PMID 35499078, 2022). "Interestingly, patients harbouring variants in CLPB protease are characterised by increased 3-MGA-uria, neutropenia, epilepsy, cataracts and movement disorders, which are some of the prominent features found in the individuals presented here." (PMID 27696117, 2017). "Heterozygous CLPB alterations were located not only in the ATP domain, e.g., p.Arg598Cys, which has been described to affect mitochondrial function and induce apoptosis leading to neutropenia, but also in the ankyrin and D2 domains, which turned out to affect CLPB oligomerization (data not shown)." (PMID 41383606, 2025).
Anxiety (10 papers, 2016 to 2024). Intense feelings of nervousness, tension, or panic often arise in response to interpersonal stresses. "Experimental studies involving mice immunized with bacterin ClpB have demonstrated diminished body weight, reduced food consumption, and ameliorated anxiety levels compared to control subjects." (PMID 38203211, 2023). "The different binding of ClpB has been associated with psychological traits in BN and BED patients, especially with more anxiety, high MADRS, and EDI-2 total score, supporting a link between bacterial ClpB and ED pathophysiology." (PMID 33416044, 2020). "Caseinolytic protease b (ClpB) is an example of a peptide produced in the gut bacteria, and ClpB has been identified as a mimetic of α-melanocyte-stimulating hormone, a neuropeptide which are supposed to be involved in satiety and anxiety signaling." (PMID 30400050, 2019). "ClpB seems to interfere with α-melanocyte-stimulating hormone involved in satiety and anxiety signaling." (PMID 28636668, 2017). "α-melanocyte-stimulating hormone (α-MSH), critical in satiety and anxiety signal transduction, is influenced by caseinolytic protease B (ClpB) produced by Escherichia coli and other Enterobacteriaceae, highlighting ClpB as a potential mediator in anxiety regulation through gut microbiota." (PMID 39717701, 2024). "A recent report suggested that Enterobacteriaceae, in particular Escherichia coli species, can produce an anorexigenic and anxiogenic protein, the caseinolyitic protease b (ClpB), which may impair αMSH involved in satiety and anxiety signaling." (PMID 33652962, 2021). "Moreover, a slightly increased plasma ClpB level in patients with eating disorders correlated inversely with their eating disorder psychopathology and with anxiety scores supporting a direct physiological effect of this natural bacterial protein." (PMID 31491982, 2019). "We showed that immunization of mice with ClpB induced the production of anti-ClpB Ig cross-reacting with α-MSH accompanied by altered food intake, body weight, anxiety and MC4-R signaling." (PMID 27445651, 2016). "More specifically, bacterial protein ClpB may act as an anorexigenic α-MSH mimetic protein directly and indirectly via triggering production of Igs cross-reactive with α-MSH, and hence, altering the effects of this endogenous peptide hormone on satiety and anxiety." (PMID 27445651, 2016).
eating disorder (8 papers, 2016 to 2021). A broad group of psychological disorders with abnormal eating behaviors leading to physiological effects from overeating or insufficient food intake. "The present study revealed that enterobacterial ClpB production is influenced by host-dependent factors, including starvation and female sex, two major risk factors for the development of eating disorders." (PMID 32272706, 2020). "Here, we studied whether ClpB production by gut bacteria can be modified by chronic food restriction and female sex, two major risk factors for the development of eating disorders." (PMID 32272706, 2020). "Breton and colleagues found an association between eating disorders and ClpB." (PMID 28636668, 2017). "Altered signaling between gut bacteria and their host has recently been implicated in the pathophysiology of eating disorders, whereas the enterobacterial caseinolytic protease B (ClpB) may play a key role as an antigen mimetic of α-melanocyte-stimulating hormone, an anorexigenic neuropeptide." (PMID 32272706, 2020). "Thus, sex-related differences expressed as both elevated plasma ClpB protein and ClpB-reactive IgM at basal conditions in female rats may at least partly contribute to the understanding of the female sex as a risk factor for eating disorder." (PMID 32272706, 2020). "Female patients with eating disorders had elevated levels of ClpB that positively correlated with the eating disorder inventory 2 score (EDI-2)." (PMID 30813265, 2019). "In accordance with a role of this protein in the physiological and pathological regulation of eating behavior, ClpB was found naturally in the plasma of healthy subjects and at a higher level in patients with eating disorders." (PMID 31635300, 2019). "In patients with eating disorders, increasing ClpB plasma levels correlated with plasma levels of anti-ClpB and anti-α-MSH Ig." (PMID 31635300, 2019). "This review shows some of the desirable characteristics in future microbiome-based solutions for eating disorders: first, the decrease of the anorexigenic ClpB protein in an AN patients, whose plasma concentration is correlated with proportion of Enterobacteriaceae in faeces." (PMID 33652962, 2021). "A recent report suggested a new role for Enterobacteriaceae in eating disorders; this family, and in particular Escherichia coli species, can produce, amongst other metabolites, an anorexigenic and anxiogenic protein, the caseinolyitic protease b (ClpB)." (PMID 28636668, 2017). "Moreover, ClpB protein plasma levels in obese mice are increased by treatment with the ClpB-producer H. alvei HA4597, in accordance with food intake reduction and patients with eating disorders show elevated ClpB plasma concentrations compared to healthy individuals." (PMID 34072450, 2021). "Finally, plasma levels of anti-ClpB IgG cross-reactive with α-MSH were increased in patients with eating disorders, and several significant correlations were found between EDI-2 scores and anti-ClpB IgG and IgM levels in AN patients, similar to previous findings with anti-α-MSH reactive Igs." (PMID 27445651, 2016).
congenital neutropenia (6 papers, 2022 to 2026). "Intriguingly, loss-of-function mutations in CLPB are associated with severe congenital neutropenia (SCN) and 3-methylglutaconic aciduria type VII (MGCA7) 20-22." (PMID 41424860, 2026). "It is important to note that the clinical manifestations of CLPB mutations (e.g., congenital neutropenia, cataracts, 3-methylglutaconic aciduria) are distinct from the adult-onset striatal neurodegeneration seen in HD." (PMID 41424860, 2026). "In humans, biallelic mutations in CLPB have been identified in children suffering from cataracts, neurodevelopmental defects, and congenital neutropenia." (PMID 35499078, 2022). "Surprisingly, we also identify monoallelic CLPB variants (G560R, R561Q, and R620H) associated with severe congenital neutropenia." (PMID 35499078, 2022). "Moreover, heterozygous missense variants of CLPB were also identified in patients with severe congenital neutropenia (SCN), and these variants were found to disrupt granulocyte differentiation of human hematopoietic progenitors." (PMID 36745679, 2023). "Interestingly, a subset of patients with mutations in CLPB is characterized not only by progressive brain dysfunction but also by congenital neutropenia." (PMID 35499078, 2022). "Thus, monoallelic mutations in CLPB may present with typical features of severe congenital neutropenia." (PMID 35499078, 2022). "Intrigued by the partial overlap in the clinical manifestation in HAX1 and CLPB deficiency, we hypothesized that HAX1 is functionally downstream of CLPB and that the phenotype of congenital neutropenia in CLPB deficiency is mediated by defective function of HAX1." (PMID 35499078, 2022). "Dominant-negative CLPB mutations may also result in isolated severe congenital neutropenia (SCN) (SCN9, MIM #619813), which cluster within the ATP-binding pocket of CLPB." (PMID 40857737, 2025). "While genotype-phenotype relationships in CLPB deficiency remain to be established in detail, some variants affecting the ANK domain, in particular CLPBY272C, are known to be associated with congenital neutropenia." (PMID 35499078, 2022).
Anorexia (5 papers, 2019 to 2021). Lack of desire to eat (loss of appetite). "In particular, AgRP expression is decreased in obese mice administered the ClpB-producer H. alvei, while in an animal model of anorexia increased ClpB plasma levels were associated with increased POMC expression." (PMID 34072450, 2021). "In that sense, autoantibodies that interreacted with the α-MSH were found elevated in subjects with anorexia and bulimia nervosa, and plasma levels of ClpB were proportional to ClpB DNA in feces." (PMID 32354351, 2020). "The increased Enterobacteriaceae and ClpB protein production is in accordance with previous papers reporting increased Enterobacteriaceae in patients with anorexia and in malnourished animals." (PMID 31635300, 2019). "The aim of this study was to highlight the role of the microbiome and the ClpB protein in deregulation and self-maintenance of anorexia pathology." (PMID 31635300, 2019). "We also measured the ClpB protein concentrations in plasma samples available from our previous study in male mice with activity-based anorexia (ABA), a rodent model of anorexia nervosa, based on the combination of restricted feeding with physical activity using a running wheel." (PMID 32272706, 2020).
acute myeloid leukemia (4 papers, 2020 to 2023). Acute myeloid leukemia (AML) is a group of neoplasms arising from precursor cells committed to the myeloid cell-line differentiation. "Up-regulated cellular level of CLPB in acute myeloid leukemia (AML) cells was found to mediate the resistance to BCL-2 inhibitor venetoclax." (PMID 36745679, 2023).